IL6 (interleukin 6)
Diseases named in the same sentence as IL6 in open-access papers (continued):
Sharing a sentence is not in itself a finding about the gene and the disease.
Sepsis (continued). "Based on the variation pattern of IL-6 and IL-10, we used combined indicators “IL-6 IL-10 ratio” and “IL-6 IL-10 differences” to further describe cytokine patterns among G+/G- sepsis patients." (PMID 36544765, 2022). "BAFF significantly promotes the secretion of serum IL-1β, TNF-α, IL-6 and other inflammatory factors in the LPS-induced sepsis model whereas neutralization of BAFF markedly inhibits pro-inflammatory factor release." (PMID 35320937, 2022). "The anti-IL-6 monoclonal antibody was demonstrated to have a protective effect on CLP sepsis rats and improve the survival rate of sepsis rats significantly." (PMID 36160407, 2022). "Mice treated with LR17 had decreased sepsis severity demonstrated by lower levels of IL-6, TNF-a, and IL-10 in serum, peritoneal and bronchoalveolar fluid, and IL-6 and TNF-a in the liver, and lung." (PMID 35784361, 2022). "The compound was found to suppress the overexpression of MMP-9, IL-1β, IL-6 and iNOS induced in LPS-induced sepsis mouse models and the TC-1 cell line in a dose-dependent manner." (PMID 36588685, 2022). "In preliminary studies we found using a more appropriate model for sepsis, i.e., mouse cecal ligation and puncture, that human eMSC reduced levels of IL-6 and TNF-α in sera after 16 h treatments with eMSC (unpublished observation MG, SB, MK)." (PMID 36551231, 2022). "Mice with LPS-induced-sepsis who were treated with BPF had lower serum levels of IL-6, TNF-α, IL-1β, CXCL1, and CXCL2 than the control mice treated with BPF." (PMID 36361915, 2022). "IL-6 was found to act as an independent predictor of 28-day mortality in sepsis patients, showing superior predictive power to procalcitonin and hypersensitive C-responsive proteins as per meta-analysis." (PMID 36452899, 2022). "Compared to common inflammatory biomarkers such as CRP, procalcitonin or IL-6, HBP is unique in that it induces vascular leakage, and therefore microcirculatory dysfunction, the hallmark of sepsis-induced organ dysfunction." (PMID 36035420, 2022). "HIF-1α was shown to be a critical determinant of sepsis promoting the production of inflammatory cytokines, including TNF-α, IL-1, IL-4, IL-6, and IL-12, which reach harmful levels during early sepsis." (PMID 35682644, 2022). "In sepsis induced by bacterial pathogens, the inflammatory cytokines such as IL-1β, IL-6, and TNF-α function as major mediators for shock and death induction." (PMID 35892383, 2022). "An analogous reduction in plasma IL-6 levels was mediated by OLE in a model of sepsis-induced myocardial injury." (PMID 36613822, 2022). "Other studies have also described increased production of cytokine in murine model of sepsis, such as IL-6, as well as the chemokine MCP-1." (PMID 35326827, 2022). "Several reports have shown that TNF-α, IL-6, and IL-10 can be used as criteria for evaluating the severity of sepsis, and that elevated levels of cytokines predict mortality in septic mice." (PMID 36743669, 2022). "In another in vitro sepsis model of the activated endothelium, miR-146a demonstrated anti-inflammatory properties by downregulating IL-8 and IL-6, and regulating the expression of heat shock protein-10 (HSP10)." (PMID 35986237, 2022). "Sepsis patients showed an increase in a few of the pro-inflammatory cytokines i.e., IL-6, IL-8, IL-18, IL-33, IP-10, MIF, MIP1a, MIP1β, and MIP3a, along with the growth factors i.e., LEPTIN, GCSF, MCSF and ESelectin." (PMID 35681439, 2022). "In preclinical studies, TAK-242 showed potent suppressive effects on the production of tumor necrosis factor-α (TNF- α), interleukin-1 (IL-1) and interleukin-6 (IL-6) in both murine and porcine models of sepsis." (PMID 35456534, 2022). "TNF-α, IL-6, and IL-1β are involved in LPS-induced tissue damage and are regarded as major regulators of severe inflammatory diseases such as sepsis." (PMID 35038964, 2022). "Activating these cells by heightened IL-6 signaling is known to lead to the pathogenesis of inflammatory diseases such as sepsis." (PMID 35615626, 2022).
Sepsis (continued). "In the receiver operating characteristic (ROC) curves of the G- sepsis group, the area under the curve (AUC) value for IL-6 and IL-10 was 0.679 (95% CI 0.561–0.798) and 0.637 (95% CI 0.512–0.762), respectively." (PMID 36544765, 2022). "A meta-analysis concluded that the nCD64 index had better diagnostic value for sepsis than PCT and IL-6." (PMID 36522701, 2022). "TNF-α seems to be the first cytokine released when systemic inflammation is observed and shows high levels within several hours after the onset of sepsis, followed by IL-1 and then IL-6." (PMID 35106183, 2022). "Our data showed that 12 h after the surgical procedure the animals had sepsis, since we observed bacterial growth in blood and increased serum concentrations of the inflammatory markers IL-6, TNF-α, KC, and MIP-2 in mice submitted to CLP compared to naïve." (PMID 35648977, 2022). "In the G+ sepsis group, IL-6 levels only exceeded 270 pg/ml in 25.6% of the patients, while 15.4% of patients exceeded 1,000 pg/ml." (PMID 36544765, 2022). "NM administration significantly diminished the plasma levels of IL-1β, TNF-α, and IL-6 compared to the sepsis control." (PMID 35345558, 2022). "Circulating miR-155-5p, with up to 701 known target genes plays a substantial role in many pathways leading to sepsis and renal injury, with a positive correlation between miR-155-5p activation and expression of the pro-inflammatory cytokines IL-6 and IL-8." (PMID 35305556, 2022). "GC is also produced endogenously in sepsis patients in whom cytokines like IL-1β, TNFα, and IL-6 induce its production from the adrenal cortex using cholesterol as a substrate to reduce inflammatory responses." (PMID 36443794, 2022). "Tracking IL‐6 in connection with CRP has been shown to have prognostic value for early detection of sepsis." (PMID 36176597, 2022). "IL-6 has been extensively studied as an early biomarker of organ dysfunction in sepsis and various acute organ injuries and as a predictive factor of morbidity and mortality in lung diseases." (PMID 35740951, 2022). "Inflammatory factors such as IL-6 and TNF-a and oxidative stress indicators such as SOD can be used as early diagnostic markers for AKI caused by sepsis, and these markers have important values for judging the prognosis of the disease." (PMID 35611245, 2022). "Multiplex detection of C-reactive protein (CRP), procalcitonin (PCT), and interleukin-6 (IL-6) is a reliable method for accurately diagnosing infections and sepsis." (PMID 35144683, 2022). "Hyperferritinemia is also related to a pro-inflammatory state in sepsis, with increases of interleukin (IL)-6, IL-18, Interferon γ, sCD163 and a decrease of the IL-10/tumor necrosis factor α ratio as quantitative markers of inflammation." (PMID 36614993, 2022). "Recently, IL-6 produced by the marginal zone B cells in animal experiments was found to be a factor that promoted the development of sepsis." (PMID 36005726, 2022). "Recent studies have shown that IL-3 plays an essential role during early sepsis: IL-3 operates upstream of key CKs [e.g., IL-6, IL-1β, and tumor necrosis factor–α (TNF-α)], and high IL-3 levels increase the risk of CK storms." (PMID 36129990, 2022). "Spearman test proved the linear correlation between IL-6 and IL-10 (r = 0.654, p < 0.001), and their combination indicators (ratio and differences) were effective in identifying G- sepsis." (PMID 36544765, 2022). "Using an in vivo LPS-induced sepsis model, we measured decreased serum levels of IL-1β, IL-1α, and IL-6 as well as increased survival of mice treated with ML133 or in Lyz2-cre-Kcnj2f/f mice compared to controls." (PMID 35729093, 2022). "In patients with severe sepsis and acute lung injury, the device was reported to have reduced the levels of IL-6, IL-8, IL-1β and TNF-α21–24,46." (PMID 35882835, 2022). "Wild-type and IL-6 knockout (KO) mice were used to establish a murine model of sepsis by cecal ligation puncture (CLP)." (PMID 35528525, 2022).
Sepsis (continued). "IL-6, IL-8 and IL-10 peak as soon as sepsis is suspected, while PCT and CRP react later, with concentration peaks at 8–16 and 16–24 h, respectively." (PMID 35626858, 2022). "CLP sepsis caused increased expression of the pro-inflammatory cytokines TNF-α, IL-1β, IL-6, as expected." (PMID 35625756, 2022). "To clarify the temporal relationship between the onset of inflammation, HS cleavage, and elevation in Ang-2 plasma levels during sepsis, we measured plasma levels of IL-6, HS, and Ang-2 using murine models of sepsis." (PMID 35763350, 2022). "Specifically, evoked supernatant concentrations of TNF, IL-6, IL-1α, IL-1β, and IL-8 were all substantially less in assays of sepsis patients’ samples, despite greater baseline concentrations and ongoing inflammatory activity when compared to controls." (PMID 35981050, 2022). "Promote the release of pro-inflammatory factors TNF-α, IL-6, IL-1β, the occurrence of inflammatory response mediates organ damage, increase the mortality of sepsis." (PMID 35463634, 2022). "Together, these results first suggested that IL-6 induced mitochondrial ROS production by inhibiting PGC–1α expression in skeletal muscle during sepsis." (PMID 35528525, 2022). "Circulating chemerin and CRP at sepsis onset outperformed procalcitonin, IL-6, IL-10 and suPAR in discriminating sepsis from septic shock." (PMID 35204801, 2022). "When IL-6 is combined with additional sepsis markers as TNF-a and CRP, the sensitivity and NPV for diagnosing EOS improves." (PMID 35449688, 2022). "The systemic inflammatory response of sepsis leads to the release of a number of proinflammatory mediators such as IL-6 and TNF-α, which induce the production of cytokine signaling inhibitors." (PMID 35719361, 2022). "Increases in the levels of TNF-α, IL-6 and IL-1β in the plasma indicated increased inflammation in the rats with sepsis." (PMID 35576220, 2022). "In the early stages of sepsis, activation of the host’s innate immune system leads to a massive release of pro-inflammatory mediators, the main ones including IL-6 and TNF-α, as well as chemokines." (PMID 36685507, 2022). "Several genetic variations in genes with immunological functions, such as CTL4, IL1-B, IL6, CD40, and HMGB1, have been reported to be associated with sepsis." (PMID 36714653, 2022). "In a polymicrobial sepsis-induced mouse model where exogeneous cGMP was administered to increase cGMP bioavailability, plasma levels of IL-6 and TNF-α are substantially reduced, and ODQ (an inhibitor of soluble GCs) showed the opposite effect." (PMID 35269704, 2022). "Sepsis is characterized by an overwhelming systemic proinflammatory response to infection and is partly attributable to a “cytokine storm”, such as IL-1β, IL-6, and TNF-α." (PMID 36064371, 2022). "But similar concentration of TNF-α and IL-6 was observed between WT-sepsis and Card9−/−-sepsis mice." (PMID 35618701, 2022). "The advantage of using IL-6 as a sepsis marker is that its concentration rises quickly once bacteremia begins, even before CRP levels rise." (PMID 35449688, 2022). "Analysis of plasmatic cytokines showed that, in all mouse strains, sepsis was accompanied by increase of IL-1β, IL-6, IL-10, TNF-α and IFN-γ." (PMID 36119089, 2022). "CLP-induced sepsis significantly increased the levels of IL-6 in the brain tissue samples in comparison with the sham group (P<0.001)." (PMID 35949300, 2022). "To conclude, Th1/Th2 cytokines, especially IL-6 and IL-10, are comparably effective in discriminating G+/G- bacteria-induced sepsis in the PICU." (PMID 36544765, 2022). "Similar results have been obtained in salivary IL-6 values in patients diagnosed with inflammatory diseases such as diabetes, sepsis and Huntington’s disease." (PMID 35054284, 2022). "In our study, the variance of IL-18 values in sepsis patients was much lower (range from 6 pg/ml to about 2000 pg/ml) than what was observed for IL-6 (from 6 pg/ml to almost 1 million pg/ml)." (PMID 36189302, 2022).
Sepsis (continued). "LPA3 can regulate IL-6/IL-8 release, reduce the formation of NETs and thrombosis, and improve the survival rate of mice with sepsis effectively." (PMID 35464399, 2022). "CLP-induced sepsis can produce inflammatory mediators including IL-6, TNF-α, and IL-1β, which aggravate inflammation." (PMID 35979014, 2022). "Although cytokines were measured at early onset of sepsis, IL-6 and IL-10 were sufficient enough for the prediction of NPMODS, in which their optimal cutoff values outperform that observed in diagnosing G- sepsis." (PMID 36544765, 2022). "ELISA results showed that the levels of inflammatory factors in the burn sepsis group were significantly higher than those in the other two groups and that IL-4, IL-6, and TNF-α continuously increased over time." (PMID 35280898, 2022). "We found that after the administration of HIF 1a, inflammatory factors TNF a and IL-6 decreased compared with the sepsis group." (PMID 36569834, 2022). "The serum levels of IL-6 and IL-1β were significantly elevated in C1q cKO mice compared with control mice, indicating an increased sepsis severity." (PMID 35983035, 2022). "It frequently results in inflammation, such as sepsis, with the primary cytokines secreted being IL-1β, IL-6, and TNF-α." (PMID 35698506, 2022). "Accordingly, the elevation of TNF-α and IL-6 in serum and liver homogenates of burn sepsis mice was markedly prohibited by glutamine treatment, which was also reversed by BLZ945." (PMID 36601059, 2022). "For example, a systematic review and meta-analysis demonstrated that TCM treatment was associated with lower levels of IL-6 and TNF-α among sepsis patients." (PMID 35722155, 2022). "Meng’s group also showed that endotoxin lipopolysaccharides via TLR4 signaling pathway to activate translocation of NF-κB and further regulate expression of pro-inflammatory genes, including TNF-α, IL-6, and IL-1β during sepsis." (PMID 35370629, 2022). "Distribution patterns of IL-6 and IL-10 in G+/G- sepsis patients were significantly different in both bloodstream and non-bloodstream infections (p < 0.05)." (PMID 36544765, 2022). "Sepsis predictably increased serum concentration of acute, proinflammatory cytokines, such as IL-6, as well as markers of endothelial dysfunction markers (ICAM-1 and angiopoietin 2)." (PMID 35286340, 2022). "Second, LPS activates inflammatory cells to secrete TNF-a, IL-1β, IL-6 and other cytokines, which mediate the development of sepsis." (PMID 35664882, 2022). "Increased serum IL-6 has been reported in chronic diseases such as rheumatoid arthritis (RA), as well as in life-threatening acute illnesses such as sepsis and cytokine release syndrome (CRS)." (PMID 36140141, 2022). "IL-1β, TNF-α, IL-10 and IL-6 are pro-inflammatory cytokines that play core roles in the pathogenesis of sepsis." (PMID 35225146, 2022). "Proinflammatory cytokines, such as TNF-alpha, IL-1b, and IL-6, have diverse effects in the regulation of immune reactions and inflammation, secondary to sepsis, hence they were the ones determined in our study." (PMID 36551850, 2022). "The reactions of some pro inflammatory cytokines such as tumor necrosis factor-alpha (TNF-α), interleukin-6 (IL-6), and interleukin-10 (IL-10) have all been characterized in the situation of sepsis, surgical damage, and trauma." (PMID 35148750, 2022). "In sepsis, mast cells are a critical source for IL-6, because mice with a mast cell-specific IL-6 depletion displayed diminished survival and bacterial clearance in a cecal ligation and puncture model." (PMID 35558068, 2022). "Patients with a poor outcome presented enhanced IDO1 activity and increased levels of KYN, KYNA, TGF-β and IL-6 in the early stage of sepsis, resulting in the development of endotoxin tolerance." (PMID 36010680, 2022).
Sepsis (continued). "Studies also showed that Wip1 expression was negatively correlated with neutrophil production of inflammatory cytokines, including TNF-α, IL-6 and IL-1β, in sepsis patients, which was mediated by the p38 MAPK-STAT1 and NF-kappaB pathways." (PMID 35538489, 2022). "Further studies concerning the interaction of circulating monocyte/macrophage and hepatocyte are of necessity to reveal the detailed effects of IL‐6/mIL‐6R signaling blockade in monocyte on regulating homeostasis of hepatocytes in SIRS/sepsis." (PMID 35548710, 2022). "XBJI treatment reduces mortality, anal temperature, and the expression of inflammatory factors such as TNF-α, IL-1β, and IL-6 when administered to mouse sepsis models." (PMID 36361915, 2022). "For G- NPMODS sepsis patients, “IL-6 IL-10 ratio” varied in a narrow range similar to that observed in G- non-NPMODS sepsis." (PMID 36544765, 2022). "The concentration of neutrophil-derived extracellular vesicles in circulation was correlated with disease severity and IL-6, and have a certain value in the prognostic assessment of sepsis." (PMID 36579343, 2022). "Blocking C1q function locally at the site of inflammation dramatically increased sepsis mortality and significantly increased the serum levels of the proinflammatory cytokines IL-6 and IL-1b in both the endotoxemia and CLP mouse sepsis models." (PMID 35983035, 2022). "Tumor necrosis factor alpha (TNF-α), interleukin 1 beta (IL-1β), and interleukin 6 (IL-6) are important proinflammatory cytokines that are considered the main cytokines in the pathogenesis of sepsis." (PMID 35106183, 2022). "The levels of IL-6 and IL-1B in lung tissue were significantly (p<0.05) increased in the sepsis group compared to the sham group." (PMID 35928365, 2022). "Animal models of sepsis have shown that MZ B cells contribute more to the increase in serum IL-6 levels than macrophages and exacerbate systemic inflammatory responses 4–8 h after injection of LPS or E. coli." (PMID 36425582, 2022). "From January 2020 onwards, we start PTX in cases of suspected sepsis when IL-6 levels are above 500 pg/mL and/or CRP levels are above 50 mg/mL at onset." (PMID 35786750, 2022). "In contrast, G+ NPMODS sepsis patients exhibited dispersed levels that implied an inconsistent relationship between IL-6 and IL-10 in such group of patients." (PMID 36544765, 2022). "SGB vigorously suppresses the sepsis-elicited release of inflammatory factors IL-6 and TNF-α, alleviating ALI in rats." (PMID 36333771, 2022). "In sepsis, macrophages are overactivated and release a large number of pro-inflammatory cytokines, including IL-1β, IL-6, TNF-α, etc., leading to organ damage and death." (PMID 36743669, 2022). "Studies have shown that during the development of sepsis, inflammatory cytokines IL-1β and IL-6 work in concert to initiate the inflammatory response and have a negative inotropic effect on the myocardium." (PMID 35223094, 2022). "Oberholzer and co-workers found that after severe sepsis, the incidence of multiple organ dysfunction syndrome, e.g., elevations in procalcitonin and interleukin-6, were significantly more frequent in males than in females." (PMID 36359231, 2022). "TNF, as an endogenous pyrogen, is able to induce fever, apoptotic cell death, cachexia, and inflammation, inhibit tumorigenesis and viral replication, and respond to sepsis via IL-1 and IL-6-producing cells." (PMID 35625362, 2022). "Sepsis induced a significant increase in the mRNA levels of the inflammatory marker IL-6 (p < 0.05) whereas the gene expression of TNF-α and IL-1β was reduced (p < 0.01 and p < 0.05, respectively)." (PMID 35795581, 2022). "Interleukins have been of recent interest as potential treatment in sepsis due to their contribution to thrombosis and their potential therapeutic effect in animal models, including pro-inflammatory IL-6 and anti-inflammatory IL-10." (PMID 36261775, 2022).